VDR (vitamin D receptor)
Diseases named in the same sentence as VDR in open-access papers (continued):
Sharing a sentence is not in itself a finding about the gene and the disease.
sickle cell anemia (3 papers, 2010 to 2021). "The present study aimed to detect the vitamin D level, lipid profile, and VDR variants of FokI, TaqI, and also GC variants in sickle cell disease (SCD) patients from Kurdistan of Iraq." (PMID 34261187, 2021). "A cohort study of 335 adults (age > 18 years old) with sickle cell anemia, followed at the Chicago Hospital in the United States, found that low vitamin D levels were associated with decreased VDR expression in peripheral blood mononuclear cells." (PMID 32686744, 2020).
upper respiratory tract infections (3 papers, 2020 to 2022). "In children with asthma, a genome analysis indicated that the VDR is one of the most important factors that regulates the susceptibility to virus-induced upper respiratory tract infections." (PMID 33671804, 2021). "In a cohort of 1462 adults from the U.K., a link between the minor VDR allele, rs4334089 SNP and the susceptibility to upper respiratory tract infections was confirmed." (PMID 33671804, 2021). "The importance of the VDR in host defense is supported by reports that the VDR genotype affects the risk of upper respiratory tract infections." (PMID 33671804, 2021). "Genetic studies have found a polymorphism in the vitamin D receptor (VDR) gene associated with upper respiratory tract infections in children and adults." (PMID 33324234, 2020).
uterine tumors (3 papers, 2021 to 2025). "They identified reduced VDR levels in more than 60% of the uterine tumors analyzed compared to the adjacent myometrium." (PMID 40868086, 2025).
vitamin D-dependent rickets (3 papers, 2022). "Mutated VDR often causes hereditary vitamin D-dependent rickets (VDDR) type II, and patients with VDDR-II are hardly responsive to physiological doses of 1,25(OH)D3." (PMID 35869242, 2022). "Vitamin D-dependent rickets (VDDR) is a group of rare, inherited defects of vitamin D metabolism (failure to synthesize 25(OH)D, or 1,25(OH)2D) or impaired vitamin D receptor signaling), resulting in end-organ resistance to 1,25(OH)2D." (PMID 34910242, 2022).
abscess (2 papers, 2021 to 2025). An inflammatory process characterized by the accumulation of pus within a newly formed tissue cavity which is the result of a bacterial, fungal, or parasitic infection or the presence of a foreign body. "Additionally, perianal complications in CD, including anal fistulae, fissures, and abscesses, did not appear to be influenced by VDR SNPs." (PMID 40076474, 2025).
adrenocortical adenomas (2 papers, 2015 to 2022). "aimed to analyze the methylation of GpG sites in the promoter of the VDR gene of a different and wider range of human adrenocortical tissues, comparing adrenocortical adenomas (ACA) with ACC tissues." (PMID 36313775, 2022). "In continuity with our previous observations, the aim of our study was to analyze methylation of GpG sites in the VDR gene promoter of a different and larger series of human adrenocortical tissues, comparing adrenocortical adenomas (ACAs) with ACCs samples." (PMID 26843863, 2015). "Methylation in the promoter region of VDR gene was found in 3/8 ACCs, while no VDR gene methylation was observed in normal adrenals and adrenocortical adenomas." (PMID 26843863, 2015).
age (2 papers, 2023 to 2024). A temporal measurement of the time period elapsed since an identifiable point in the life cycle of an organism. "Overall, the VDR-mediated vitamin D neuroprotective, anti-inflammatory and neurovascular mechanisms may predominantly contribute to its beneficial effects in age-related ND treatment and prevention." (PMID 36831327, 2023). "In conclusion, in this study, we first demonstrated that the depletion of Mic60 is related to the development of age-induced NAFLD and that vitamin D can prevent NAFLD by upregulating Mic60 expression in a VDR-RXR-dependent manner." (PMID 38172593, 2024).
aging (2 papers, 2024 to 2026). A developmental process that is a deterioration and loss of function over time. "Vitamin D receptor (VDR) signaling plays a crucial role in skin homeostasis and represents a promising therapeutic target for inflammatory senescence-associated skin aging." (PMID 42256529, 2026).
Alcohol (2 papers, 2014 to 2018). "We aimed to explore a potential relationship between FokI VDR polymorphism and impulsiveness in alcohol-dependent (AD) patients." (PMID 25059118, 2014). "However, it has not yet been proven whether polymorphic variants of the VDR gene can affect the mental state of alcohol-dependent (AD) individuals by modulating expression of the array of genes related to central nervous system function." (PMID 25059118, 2014).
alopecia totalis (2 papers, 2016 to 2024). Alopecia totalis is a form of alopecia areata, an inflammatory disease of the hair follicle, characterized by a complete loss of hair of the entire scalp which becomes glabrous. "Notably, loss of the VDR, but not CYP27B1, in mice and humans leads to alopecia totalis." (PMID 39321290, 2024).
amyloidosis (2 papers, 2021 to 2023). A disorder characterized by the localized or diffuse accumulation of amyloid protein in various anatomic sites.
anaplastic thyroid cancer (2 papers, 2022 to 2024). "Furthermore, VDR expression was often lost in anaplastic thyroid cancer (ATC)." (PMID 37991208, 2024). "Unlike DTC, in many anaplastic thyroid cancer cases, loss of VDR expression was reported." (PMID 36362448, 2022).
antithrombin deficiency (2 papers, 2016 to 2024). "Additionally, our study suggests that other elements of this pathway, such as the vitamin D receptor (VDR) or the retinoid X receptor (RXR), might also play a role in the variability of antithrombin in the general population, in antithrombin deficiency and in the risk of thrombosis." (PMID 27003919, 2016).
benign breast disease (2 papers, 2019 to 2026). "Previous research have found expression of VDR to be higher in in situ and infiltrative carcinoma compared to benign breast disease or normal tissue, but others argue the opposite." (PMID 31358030, 2019).
brain injury (2 papers, 2015 to 2024). Acute and chronic (see also brain INJURIES, CHRONIC) injuries to the brain, including the cerebral hemispheres, CEREBELLUM, and brain STEM. "Several lines of evidence show that vitamin D hormone has neuroprotective effects following ischemic brain injury, but the role of vitamin D and the VDR in H/R-induced BBB permeability has not yet been investigated." (PMID 25815722, 2015).
campylobacteriosis (2 papers, 2021). Infections with bacteria of the genus campylobacter. "Our RNA-Seq data from campylobacteriosis patients demonstrate inhibition of VD receptor (VDR) downstream targets, consistent with suppression of immune function." (PMID 34445577, 2021).
cardiac interstitial fibrosis (2 papers, 2015 to 2018). "Of note, we found little evidence of cardiac interstitial fibrosis in WT or VDR mutant mice, 8 weeks post-MI." (PMID 30273386, 2018). "Characterization of VDR knockout mice has demonstrated increased cardiac fibrosis, however cardiomyocyte-specific VDR deletion does not result in increased interstitial cardiac fibrosis, suggesting that non-myocyte VDR contributes to the observed fibrotic phenotype." (PMID 26061181, 2015).
cerebral infarction (2 papers, 2022). An ischemic condition of the brain, producing a persistent focal neurological deficit in the area of distribution of the cerebral arteries. "1,25-D3 reduced cerebral infarction volume, increased the recovery of CBF and expressions of VDR, TGF-β, p-Smad2, p-Smad3, and VEGF, significantly increased IB4+ tip cells and CD31+ vascular length in the peri-infarct area compared with the DMSO group." (PMID 35369317, 2022).
Chagas disease (2 papers, 2016 to 2024). A parasitic infection caused by Trypanosoma cruzi. "Studies are needed to evaluate the expression of the VDR in immune cells of patients with Chagas disease, associating it with serum vitamin D dosage." (PMID 39267468, 2024). "In addition, studies exploring the expression of the VDR in immune cells of patients with Chagas' disease and its association with serum vitamin D levels would provide crucial information on the mechanisms underlying the effects of vitamin D in this context." (PMID 39267468, 2024). "In this study, four genetic variants of the VDR gene were tested for association with risk of infection by T. cruzi and/or development of CCC in a population from a Colombian endemic region of Chagas disease." (PMID 27502545, 2016).
Cholestatic liver disease (2 papers, 2013 to 2023). "While modulating VDR activity may be a potential target for treating cholestatic liver diseases, it is important to note that VDR activity can affect calcium metabolism and influence blood calcium levels." (PMID 37120573, 2023).
Chronic Lymphocytic Leukemia (2 papers, 2013 to 2021). "The previous study of LCLs had shown VDR enrichment near regions associated with chronic lymphocytic leukemia." (PMID 23849224, 2013).
chronic myeloid leukemia (2 papers, 2020 to 2024). "This review will summarize recent research findings and discuss the therapeutic potential of selected NRs in acute and chronic myeloid leukemia, focusing on RAR, VDR, PPAR, and retinoid X receptor (RXR)." (PMID 32824945, 2020).
colon adenoma (2 papers, 2011). An adenoma that arises from the colon. "Genetic variants in the VDR gene have been previously associated with CRC and colonic adenoma risk; however, VDR association results have been inconsistent." (PMID 22046258, 2011).
cutaneous leishmaniasis (2 papers, 2023 to 2024). Leishmaniasis affecting the skin. "(2023) identified, in Saudi patients, the association of polymorphisms of the VDR gene with parasite load and susceptibility to cutaneous leishmaniasis caused by Old World Leishmania." (PMID 39844838, 2024). "The haplotype frequencies of the studied four vitamin D receptor gene polymorphisms in patients with cutaneous leishmaniasis (CL) and controls." (PMID 37319132, 2023). "A remarkable lack of data exists in humans about the contribution of vitamin D and polymorphisms of the VDR gene in protozoan infections, especially cutaneous leishmaniasis (CL)." (PMID 37319132, 2023). "Genotypes and allele frequencies for vitamin D receptor (VDR) BsmI, ApaI, TaqI, and FokI in patients with cutaneous leishmaniasis and control subjects." (PMID 37319132, 2023). "Serum levels of vitamin D according to vitamin D receptor genotypes among patients with cutaneous leishmaniasis with no history of vitamin D therapy." (PMID 37319132, 2023). "The Ridley parasitic load index (RPI) according to vitamin D receptor genotypes among patients with cutaneous leishmaniasis with no history of vitamin D therapy." (PMID 37319132, 2023).
developmental dysplasia of the hip (2 papers, 2007 to 2025). A spectrum of hip abnormalities commonly presenting in infancy involving the relationship between the femoral head and the acetabulum and that includes subluxation or dislocation at rest or upon provocation. "We investigated the association of developmental dysplasia of the hip (DDH) and primary protrusion acetabuli (PPA) with Vitamin D receptor polymorphisms Taq I and Fok I and oestrogen receptor polymorphisms Pvu II and Xba I. 45 patients with DDH and 20 patients with PPA were included in the study." (PMID 17598904, 2007).
diabetic ketoacidosis (2 papers, 2022 to 2023). The metabolic condition resulted from uncontrolled diabetes mellitus, in which the shift of acid-base status of the body toward the acid side because of loss of base or retention of acids other than carbonic acid is accompanied by the accumulation of ketone bodies in body tissues and fluids. "The expression of the vitamin D receptor on pancreatic beta cells appears to have a role in insulin secretion, and low vitamin D levels could facilitate the onset of diabetic ketoacidosis." (PMID 36364863, 2022).
endometrioid carcinoma (2 papers, 2024 to 2025). "Notably, VDR expression patterns appear to correlate with histological grade and differentiation status, as demonstrated in endometrioid carcinoma, where VDR displacement was found to be significantly associated with lower histological grade." (PMID 41394244, 2025).
epidermal cyst (2 papers, 2016 to 2024). "Moreover, the presence of epidermal cysts/keratocanthomas prompted us to ask if VDR ablation induced or exacerbated other extra-colonic lesions in Apc1638N/+animals." (PMID 27768599, 2016).
essential tremor (2 papers, 2020 to 2023). A relatively common disorder characterized by a fairly specific pattern of tremors which are most prominent in the upper extremities and neck, inducing titubations of the head. "He demonstrated for the first time that the rs2228570 variant of the vitamin D receptor gene is, in fact, associated with sporadic essential tremor overall and particularly in male patients." (PMID 32908795, 2020). "There seems to be a link between the occurrence of essential tremor and vitamin D receptor polymorphism." (PMID 32908795, 2020).
female infertility (2 papers, 2022 to 2024). Diminished or absent ability of a female to achieve conception. "Specifically, VDR is associated with female infertility, whereas CEBPB has been described as relevant factor for female reproduction for its role in ovarian follicle development, together with SMAD3 and ESR2." (PMID 36589743, 2022).
fibroma (2 papers, 2016 to 2021). A non-metastasizing neoplasm arising from the fibrous tissue. "Under light microscopy, we observed a scarcity of brown nuclei stained by anti-VDR antibody in the fibroma samples and many nuclei stained in the adjacent normal myometrial samples." (PMID 33952298, 2021).
hepatitis B infection (2 papers, 2019 to 2022). "Certain vitamin D receptor gene (VDR a/a) polymorphisms have been linked to greater severity of hepatitis B infection and a higher viral load." (PMID 31252594, 2019). "Vitamin D receptor (VDR) polymorphism partly regulates the immune system and is associated with hepatic flare in chronic Hepatitis B virus infection (HBV)." (PMID 36490235, 2022). "In addition, polymorphisms in the T/T allele of exon 9 of the VDR gene (but not intron 8 polymorphisms) are associated with occult hepatitis B infection." (PMID 31252594, 2019).
hip fracture (2 papers, 2019 to 2022). Traumatic or pathological injury to the hip in which the continuity of either the femoral head, femoral neck, intertrochanteric or subtrochanteric regions is broken. "A recent report has shown that the ratio of 24,25-dihydroxyvitamin D3 (24,25(OH)2D3) to 25(OH)D is a better risk indicator for hip fracture than 25(OH)D because this ratio reflects vitamin D receptor (VDR) activity." (PMID 35684001, 2022).
hyperandrogenism (2 papers, 2019 to 2023). Excessive secretion of androgens from the adrenal glands or gonads. "In conclusion, VDR gene variants may be involved in the pathogenesis of PCOS via their effects on hyperandrogenism and IR." (PMID 31870342, 2019). "VDR polymorphisms are known to be associated with metabolic and endocrine parameters of PCOS, including IR and hyperandrogenism." (PMID 31870342, 2019). "Because IR and hyperandrogenism are key features of PCOS, VDR gene variants may contribute to the pathogenesis of PCOS." (PMID 31870342, 2019). "Our results suggest that the lack of vitamin D signaling combined with hyperandrogenism impairs the acute compensation after CAO, as short-term chronic androgen exposure with VDR inactivity resulted in prolonged hypoperfusion in all regions of the ipsilateral cortex." (PMID 37764653, 2023).
Hyperbilirubinemia (2 papers, 2012 to 2021). An increased amount of bilirubin in the blood. "We examined the effect of 1α-hydroxyvitamin D3 treatment on hyperbilirubinemia induced by intravenous bilirubin infusion in wild-type mice and found that VDR activation did not increase the rate of clearance of exogenous bilirubin (unpublished data)." (PMID 23240054, 2012).
hyperlipidemia (2 papers, 2019 to 2021). "In summary, we identified that the VD/VDR signaling system balanced the utilization of energy substrates to protect the heart against hyperlipidemia." (PMID 33981701, 2021). "Taken together, VD/VDR upregulated SIRT3 and mitochondrial respiratory chain complexes, while decreasing hyperlipidemia-induced oxidative damage." (PMID 33981701, 2021).
Hypocalciuria (2 papers, 2020 to 2024). An abnormally decreased calcium concentration in the urine. "This VDR variant is also present in both parents, though only the father presents with hypocalciuria." (PMID 38519529, 2024). "Importantly, although a history of hypocalciuria was reported within the family, the parents only presented with the variant p.Val347Ile in the VDR gene." (PMID 32997713, 2020).
hypophosphatemic rickets (2 papers, 2023 to 2024). Rickets due to low serum phosphate concentrations, the cause of which can be nutritional or genetic. "Consequently, genetic disorders caused by inactivating GalnT3 and Fam20C mutations, such as familial tumoral calcinosis and hypophosphatemic rickets, are unlikely to be influenced by VDR-mediated regulation of FGF23 cleavage." (PMID 37681408, 2023).
IgA nephropathy (2 papers, 2019 to 2021). "IgA nephropathy patients carrying the VDR FokI TT genotype have an increased risk of renal dysfunction." (PMID 31218132, 2019). "Studies have shown that the occurrence and development of IgA nephropathy (IgAN) are genetically susceptible, but the relationship between vitamin D receptor (VDR) gene polymorphisms and renal function in IgAN patients is unclear." (PMID 31218132, 2019).
infarction (2 papers, 2022 to 2023). A localised pathological necrosis of tissue resulting from obstruction of the blood supply usually by a thrombus, an embolus, or vascular torsion. "In western blot and RT-qPCR, we were surprised to find that 1,25-D3 could promote the expression of VDR, VEGF and TGF-β signaling pathway proteins 3 days after infarction." (PMID 35369317, 2022).
intestinal cancer (2 papers, 2012 to 2024). "VDR expression in CAF of intestinal cancer tissue stroma is more associated with prognosis." (PMID 38600588, 2024). "In intestinal cancer cells, genistein up-regulates VDR transcription and VDR expression possibly through the ER and MAPK signaling pathway but no reported increase in Ca absorption." (PMID 23201836, 2012).
intestinal tumor (2 papers, 2016 to 2022). "Overall intestinal tumor incidence in the Apc mutant rat was unaffected by VDR loss: ApcPirc/+VDR+/+ (36/36) and ApcPirc/+VDR−/− (35/36, P=0.3)." (PMID 35662320, 2022). "These VDR−/− rats were then crossed with ApcPirc/+ rats, which are predisposed to the development of intestinal neoplasms." (PMID 35662320, 2022). "By contrast, when tumors are initiated by mutation in the Adenomatous polyposis coli gene, which results in nuclear accumulation of β-catenin, we determined whether loss of vitamin D hormone signaling through VDR further promotes the growth or progression of intestinal tumors." (PMID 35662320, 2022).
Kaposi's sarcoma (2 papers, 2024 to 2026). A malignant neoplasm characterized by a vascular proliferation which usually contains blunt endothelial cells. "Another study found that VDR agonists activate autophagy in Kaposi’s sarcoma cells by inhibiting the PI3K/Akt/mTOR signaling pathway." (PMID 41141390, 2026). "In various cancer contexts, VD has been shown to engage with VDR and inhibit tumor progression through the PI3K-AKT-mTOR pathway, as observed in Kaposi's sarcoma cells 96 and non-small cell lung cancer." (PMID 38230221, 2024).